TARDBP (TAR DNA binding protein)
Diseases named in the same sentence as TARDBP in open-access papers (continued):
Sharing a sentence is not in itself a finding about the gene and the disease.
Atrophy (27 papers, 2011 to 2026). Any weakening or degeneration, especially through lack of use. "Both two bvFTD individuals with the I383V variant in TARDBP gene fell into the Limbic-predominant subtype, consistent with previous observations that I383V variant was associated with predominant atrophy of temporal lobes and hippocampus." (PMID 37609205, 2023). "Compared with controls, VBM showed a circumscribed, distinctive atrophy of the right lateral parietal cortex in MND patients with a TARDBP mutation, confirmed by GM volumetric reduction of the right angular gyrus." (PMID 35911889, 2022). "The atrophy in these brain regions correlates with the accumulation of pathological lesions composed of inclusions with various compositions of disease proteins, of which TAR DNA-binding protein 43 (TDP-43) is the most common (FTLD-TDP)." (PMID 40619440, 2025).
primary progressive aphasia (23 papers, 2013 to 2026). Primary progressive aphasia (PPA) is a neurodegenerative disorder, characterized by a primary dissolution of language, with relative sparing of other mental faculties for at least the first 2 years of illness. "The different phenotypes (behavioural variant, primary progressive aphasias etc.), monogenic causes and aggregated proteins in brain tissue (mainly TAR DNA-binding protein 43; TDP-43 or tau) can challenge the ambitions to find fluid biomarkers for FTD." (PMID 34838088, 2021).
Encephalopathy (22 papers, 2020 to 2026). Encephalopathy is a term that means brain disease, damage, or malfunction. "In a recent study, an AD subtype—limbic-predominant age-related TAR DNA-binding protein 43 (TDP-43) encephalopathy (LATE)—has been defined." (PMID 33672406, 2021).
familial amyotrophic lateral sclerosis (22 papers, 2009 to 2025). An instance of amyotrophic lateral sclerosis that is caused by an inherited modification of the individual's genome. "Mutations in the TARDBP gene, which encodes the Tar DNA binding protein, have been shown to causes of both familial amyotrophic lateral sclerosis (FALS) and sporadic ALS (SALS)." (PMID 23874513, 2013). "We studied the reproductive parameters of mice hemizygous for TDP-43A315T transgene, which are viable, fertile, and express a mutant human TAR DNA binding protein (hTDP-43) cDNA harboring an amino acid substitution associated with familial amyotrophic lateral sclerosis (fALS)." (PMID 33297584, 2020). "Here we provide evidence demonstrating pathogenic differences in CSF from patients with sporadic amyotrophic lateral sclerosis and familial amyotrophic lateral sclerosis patients with mutations in SOD1, C9orf72 and TARDBP." (PMID 36043141, 2022).
spinal muscular atrophy (21 papers, 2008 to 2025). A motor neuron disease that affect the muscles, and characterized by muscle weakness and atrophy resulting from progressive degeneration and irreversible loss of the anterior horn cells in the spinal cord (i.e., lower motor neurons) and the brain stem nuclei. "These include spinal muscular atrophy (SMA) caused by mutations in the survival motor neuron 1 (SMN1) gene and amyotrophic lateral sclerosis 10 (ALS10) caused by mutations in the TAR DNA binding protein or TDP-43 gene." (PMID 39070547, 2024).
sporadic amyotrophic lateral sclerosis (21 papers, 2011 to 2026). Sporadic amyotrophic lateral sclerosis is a amyotrophic lateral sclerosis in which there is no known cause, such as no family history. "To investigate the genetic and clinical features of Chinese sporadic amyotrophic lateral sclerosis (SALS) patients with TARDBP mutations, we carried out a genetic analysis in a cohort of 391 SALS patients and explored the clinical manifestations of patients with TARDBP variants." (PMID 34333853, 2021).
breast carcinoma (20 papers, 2015 to 2026). "TAR DNA-binding protein 43 (TDP43) was detected in stage 3 breast cancer samples." (PMID 31945087, 2020). "In the breast cancer tissue group, the three most stably expressed genes (with the lowest M values) were SF1, THRAP3, and TARDBP, while GAPDH, DNAJC8, and B2M were the least stably expressed genes." (PMID 34895237, 2021). "In the breast cancer tissue group DNAJC8, RPL13A, and TARDBP were the most stably expressed genes, while ACTB, B2M, and GAPDH were the least stably expressed genes." (PMID 34895237, 2021). "AR12 and the breast cancer drug neratinib (NER) rapidly reduced expression of Tau, amyloid precursor protein (APP), superoxide dismutase 1 (SOD1) and TAR DNA-binding protein 43 (TDP-43)." (PMID 36227739, 2022). "In addition, THRAP3, TARDBP, and YY1 were the most stably expressed genes in the breast cancer cell lines, while B2M, TUBA1A, and ACTB were the least stably expressed genes." (PMID 34895237, 2021). "SRSF3 stabilizes the mRNA of TAR DNA-binding protein-43 (TDP43) by inhibiting the NMD pathway in triple-negative breast cancer, thereby maintaining the stemness of breast cancer stem cells." (PMID 39034387, 2024).
viral infection (18 papers, 2013 to 2025). "TARDBP has been known to promote translation and RNA stability and it has also been shown to play important role in viral infection." (PMID 32780783, 2020). "However mutations in genes such as copper/zinc superoxide dismutase (SOD1), fused in sarcoma (FUS) and TAR DNA binding protein (TARDBP), have also been described in SALS patients; also environmental causes such as smoking and viral infection are linked to ALS." (PMID 23533690, 2013). "Next, to confirm whether IFNβ overproduction during viral infection is a common phenomenon in all ALS patients, we examined IFNβ production by cells from several ALS patients with mutations in the ALS-causative genes, SOD1, FUS, ANG, FIG4, and TARDBP." (PMID 37352136, 2023).
brain injury (14 papers, 2014 to 2025). Acute and chronic (see also brain INJURIES, CHRONIC) injuries to the brain, including the cerebral hemispheres, CEREBELLUM, and brain STEM. "Traumatic brain injury was associated with increased odds ratio [1.79, confidence interval 1.18–2.72] of having a higher neurofibrillary tangle stage and phosphorylated TAR DNA binding protein 43 (OR 2.48, confidence interval 1.35–4.54)." (PMID 35950093, 2022).
hepatocellular carcinoma (14 papers, 2018 to 2024). A malignant tumor that arises from hepatocytes. "TAT-activated regulatory DNA binding protein (TARDBP), which is highly expressed in hepatocellular carcinoma (HCC), regulates glycolysis by inducing the expression of the platelet isoform PFK1 (PFKP)." (PMID 37164974, 2023). "Recent studies have shown that TARDBP plays an important role in many tumours, including leukaemia, Ewing sarcoma and hepatocellular carcinoma (HCC)." (PMID 34830998, 2021). "In vitro, TARDBP regulates glycolysis in a hepatocellular carcinoma cell line through the miRNA-mediated post-transcriptional regulation of a key rate-limiting glycolytic enzyme phosphofructokinase (PFKP)." (PMID 30509290, 2018). "In hepatocellular carcinoma (HCC), TARDBP-PFKP-miR-520 axis enhanced glycolysis to inhibit the growth of HCC cells." (PMID 31534516, 2019). "In the realm of cancer research, particularly hepatocellular carcinoma (HCC), TAR DNA-binding protein (TARDBP) has transitioned from being associated with neurodegenerative diseases to emerging as a significant molecule in oncology due to its aberrant expression in HCC and other malignancies." (PMID 38947395, 2024).
Perry syndrome (14 papers, 2013 to 2025). Perry syndrome is a rare inherited neurodegenerative disorder characterized by rapidly progressive early-onset parkinsonism, central hypoventilation, weight loss, insomnia and depression. "Apart from neuronal loss, TAR DNA-binding protein 43 (TDP-43) pathology is another neuropathological feature of Perry syndrome." (PMID 41536567, 2022).
depression (13 papers, 2020 to 2026). "Further, patients with ALS exhibit phosphorylated 43-kDa TAR DNA-binding protein aggregates in hypothalamic regions, which may also disrupt sleep patterns and, thus, increase the risk of depression." (PMID 41018179, 2025). "Research exploring the link between TAR DNA-binding protein 43 (TDP-43) and depression, particularly in the context of Limbic Predominant Age-Related TDP-43 Encephalopathy (LATE), remains sparse, with only a handful of studies investigating this relationship." (PMID 39767653, 2024).
Obesity (13 papers, 2013 to 2025). Accumulation of substantial excess body fat. "In fat metabolism, conditional TARDBP KO mice induced with tamoxifen die rapidly, displaying dramatic fat loss, increased fatty acid consumption, and downregulation of the obesity-associated gene TBC1D1, resulting in severe disruption of the body’s fat metabolism." (PMID 40941402, 2025). "TARDBP has also been implicated in the obesity pathogenesis." (PMID 40941402, 2025). "Conversely, transgenic mice overexpressing TARDBP develop marked obesity characterized by excessive fat deposition and adipocyte hypertrophy compared with non-transgenic littermates." (PMID 40941402, 2025). "Studies found that TET1 upregulated TAR DNA-binding protein (TARDBP) and enhanced the function of obesity-driven cancer stem cells in triple-negative breast cancer (TNBC)." (PMID 40014756, 2025). "In first step, obesity triggers systemic hyperglycemia, which activates TET1 to produce higher levels of the DNA binding protein TARDBP via increased OGT substrate levels." (PMID 37231419, 2023).
lung carcinoma (12 papers, 2018 to 2025). "The HNRNPA2B1 levels were positively associated with TARDBP (R = 0.83), DHX9 (R = 0.73), HNRNPR (R = 0.77), SRSF1 (R = 0.79), HNRNPD (R = 0.75), and HNRNPM (R = 0.78) genes in lung cancer (all P < 0.001)." (PMID 35529270, 2022).
corticobasal syndrome (11 papers, 2015 to 2025). Corticobasal syndrome (CBS) is a rare neurodegenerative disease characterized by multifaceted motor system dysfunctions and cognitive defects such as asymmetric rigidity, bradykinesia, limb apraxia, and visuospatial dysfunction. "In a series of 252 FTD and corticobasal syndrome patients screened for TARDBP mutations, only 1.9% of the cases were positive." (PMID 25853458, 2015). "Direct DNA sequencing of TARDBP exon 6 was performed in a large Italian cohort of 735 patients affected by PD (354 familial and 381 sporadic) and 142 affected by atypical parkinsonism, including 39 corticobasal syndrome (CBS) and 103 progressive sopranuclear palsy (PSP)." (PMID 36247987, 2022).
glioma (11 papers, 2015 to 2025). A benign or malignant brain and spinal cord tumor that arises from glial cells (astrocytes, oligodendrocytes, ependymal cells). "Our findings suggest that the TARDBP gene and the protein it encodes play important roles in glioma patients." (PMID 37147573, 2023). "After confirming that the expression of the TARDBP gene is closely related to the survival prognosis of patients, we aimed to gain insight into the role of the TARDBP gene and its expression products in the development of tumours in glioma patients." (PMID 37147573, 2023). "Knowing that the expression of the TARDBP gene correlates with the overall survival (OS) rate of the patient, we attempted to build a model that predicts the survival rate of glioma patients." (PMID 37147573, 2023). "In the validation group, the expression level of the TARDBP gene was also an independent predictor of glioma patient OS." (PMID 37147573, 2023). "To determine the function of the TARDBP gene in glioma patients, we selected the top 500 correlated genes from Pearson correlation analysis (R > 0.5, descending arrangement, p < 0.05) and conducted DAVID analysis." (PMID 37147573, 2023). "Taking advantage of the convenience and specificity of the CGGA database, which collects and organizes a large amount of data, we aimed to illustrate the relationship between the expression of the TARDBP gene and patients with glioma." (PMID 37147573, 2023). "Cox survival analysis was performed to determine the relationship between TARDBP gene expression and the overall survival of glioma patients." (PMID 37147573, 2023). "The expression of the TARDBP gene has a significant correlation with the overall survival of glioma patients." (PMID 37147573, 2023). "We found that the expression level of the TARDBP gene is an independent predictor of the OS of glioma patients." (PMID 37147573, 2023). "In summary, we found that the TARDBP gene in glioma patients is mainly located in intracellular compartments, such as in the nuclear plasma and nucleus, and involved in processes such as RNA splicing and mRNA processing." (PMID 37147573, 2023). "To further evaluate the predictive ability of TARDBP gene expression, we constructed a prediction model to predict the OS of glioma patients." (PMID 37147573, 2023). "It is possible that higher expression of the TARDBP gene can reduce relapse in postsurgical glioma patients." (PMID 37147573, 2023). "The expression of the TARDBP gene has a significant correlation with glioma patient survival." (PMID 37147573, 2023). "To determine whether the TARDBP gene can predict glioma patient prognosis, we conducted Kaplan‒Meier and Cox proportional hazard model analyses of the training and validation groups." (PMID 37147573, 2023). "TDP-43, a product encoded by the TARDBP gene, is mainly involved in the binding of RNA and proteins in the occurrence and development of disease in patients with glioma." (PMID 37147573, 2023). "Using the Chinese Glioma Genome Atlas (CGGA) database, we analysed the TARDBP gene expression profile in various patients and explored whether the expression of the TARDBP gene was associated with overall survival." (PMID 37147573, 2023). "However, research reports focused on the role of the TARDBP gene in the occurrence, development and prognosis of glioma are rare." (PMID 37147573, 2023). "However, the relationship between the TARDBP gene and its expression products and patients with glioma remains to be further explored." (PMID 37147573, 2023). "In glioma, SNHG12 targeting of miR-101-2 leads to enhanced cell growth, malignant progression via TDP43 (TAR DNA-binding protein 43), and enhanced proliferation/migration capacity due to the association with the Hu antigen R." (PMID 32318335, 2020). "We first analysed whether various factors, such as age, expression of the TARDBP gene, radiotherapy, and TMZ chemotherapy, were related to the survival prognosis of glioma patients." (PMID 37147573, 2023).
triple-negative breast carcinoma (11 papers, 2020 to 2025). An invasive breast carcinoma which is negative for expression of estrogen receptor (ER), progesterone receptor (PR), and human epidermal growth factor receptor 2 (HER2). "Studies have shown that TAR DNA binding protein 43 (TDP-43) is highly expressed in triple-negative breast cancer (TNBC) and correlates with poor patient prognosis." (PMID 40129567, 2025). "For example, TDP43 (TAR DNA-binding protein-43) regulates alternative splicing in triple-negative breast cancer (TNBC), indicating its critical role in this heterogeneous cancer." (PMID 40600167, 2025). "TAR DNA-binding protein (TDP43) is overexpressed in triple-negative breast cancer (TNBC) and is a major regulator of unique alternative splicing in TNBC." (PMID 37875914, 2023). "We previously identified a unique AS profile in triple-negative breast cancer (TNBC), which is regulated by the splicing regulator TAR DNA-binding protein-43 (TDP43), thus indicating the crucial role of TDP43 in heterogeneous TNBC." (PMID 35504883, 2022).
HIV-1 infection (10 papers, 2014 to 2025). The type species of lentivirus and the etiologic agent of acquired immunodeficiency syndrome (AIDS). "In this study, we found that HIV-1 infection can induce proteolytic cleavage and aberrant aggregation of TAR DNA-binding protein 43 (TDP-43), a pathological protein associated with various severe neurological disorders." (PMID 39242776, 2024). "Similarly, transactive response DNA-binding protein (TARDBP/TDP-43) suppresses the production of HIV-1 viral particles, yet an NLS-deficient TARDBP/TDP-43 mutant fails to regulate HIV-1 infection." (PMID 40459262, 2025). "A key restriction factor for HIV-1 infection that we characterized is the cytoplasmic enzyme HDAC6 (histone deacetylase 6), and more recently the transactive response of the DNA-binding protein (TARDBP or TDP-43) together with HDAC6 (i.e., the TDP-43/HDAC6 axis)." (PMID 36140273, 2022).
spinocerebellar ataxia (10 papers, 2012 to 2025). "Extensive genetic testing has been performed in various cases, which included ALS genes (C9orf72, FUS, SOD1, TARDBP), oculopharyngeal muscular dystrophy (PABPN1), Kennedy disease (AR), panels for spinocerebellar ataxia as well as whole-exome sequencing." (PMID 33842068, 2021).
progressive neurodegenerative disorder (9 papers, 2011 to 2025). "Amyotrohpic lateral scleorsis (ALS) is a progressive neurodegenerative disorder that affects motor and extra-motor systems, and shares the pathologic hallmark of neuronal inclusions immunoreactive to TAR-DNA binding protein of ∼43 kD (TDP-43) with many cases of frontotemporal degeneration (FTD)." (PMID 23460879, 2013).
Stroke (9 papers, 2018 to 2025). Sudden impairment of blood flow to a part of the brain due to occlusion or rupture of an artery to the brain. "The regulatory effects of the core genes of the ALS pathway (SOD1, FUS, TARDBP) on ROS metabolism and inflammatory responses are common pathological drivers of Osteoporosis and stroke." (PMID 41379792, 2025).
neuropathy (7 papers, 2018 to 2025). A disorder affecting the nervous system that manifests with pain, tingling, numbness, and/or muscle weakness. "The downstream mechanisms leading from DNAJB2 loss of function to neuropathy are largely unknown, but accumulation of phosphorylated TARDBP in patient skin biopsies suggests that TARDBP aggregation has a potential role in the pathomechanism." (PMID 37070754, 2023).
ischemic stroke (6 papers, 2018 to 2025). A stroke disorder caused by obstruction of blood flow to the brain, due to thrombotic (local blood clot formation) or embolic (due to a blood clot or other material traveling from another site) event. "We further showed that inhibiting PTEN induces the nuclear TDP-43 (TAR DNA-binding protein-43) increase, and also produce the GABAA receptor expression and function enhancement to protect against the ischemic stroke induced neuronal death in vivo and in vitro." (PMID 29882124, 2018).
osteosarcoma (6 papers, 2020 to 2025). A usually aggressive malignant bone-forming mesenchymal neoplasm, predominantly affecting adolescents and young adults. "Based on this system, we generated a human osteosarcoma cell line, which allows for the inducible expression of an EGFP fusion of the TAR DNA‐binding protein 43 (TDP‐43), which has been linked to neurodegenerative diseases." (PMID 36062323, 2022).
leukemia (5 papers, 2021 to 2026). A malignant (clonal) hematologic disorder, involving hematopoietic stem cells and characterized by the presence of primitive or atypical myeloid or lymphoid cells in the bone marrow and the blood. "TARDBP has been shown to directly regulate ADAR1 expression in liver cancer and leukemia cell line models." (PMID 38773080, 2024).
schizophrenia (5 papers, 2012 to 2024). A major psychotic disorder characterized by abnormalities in the perception or expression of reality. "Intriguingly, it has been shown that schizophrenia patients exhibit tau and TAR DNA binding protein-43 (TDP-43) deposits in the brain, which is typical of FTLD brains." (PMID 36233357, 2022).
respiratory failure (4 papers, 2016 to 2025). The significant impairment of gas exchange within the lungs resulting in hypoxia, hypercarbia, or both, to the extent that organ tissue perfusion is severely compromised. "TARDBP gene variants, that encode the transactivation response DNA-binding protein, 43 kDa, represent a genetic component of ALS causation and are particularly linked to rapid course, early respiratory failure, and severe upper and lower motor neuron loss." (PMID 40869392, 2025).